INS (insulin)
Diseases named in the same sentence as INS in open-access papers (continued):
Sharing a sentence is not in itself a finding about the gene and the disease.
type 2 diabetes (continued). "The onset of type 2 diabetes occurs when beta-cell function cannot compensate for the high levels of insulin needed due to the peripheral insulin resistance." (PMID 21191145, 2011). "A combination of oligofructose and polydextrose was reported to increase insulin and C-peptide levels in type-2 diabetic patients." (PMID 22205091, 2011). "In tumour-bearing mice, insulin insensitivity preceded weight loss and administration of Rosiglitazone, a drug used in the treatment of type 2 diabetes, improved insulin sensitivity and attenuated skeletal muscle proteolysis." (PMID 21970879, 2011). "Insulin fibrillization poses a problem for the treatment of Type II diabetes where insulin amyloid deposits have been observed at sites of repeated insulin injection." (PMID 22272138, 2011). "While the recommended quantity of mealtime insulin per day differs by patient, these levels are significantly lower than would be expected in a group of patients with adequately managed type 2 diabetes using mealtime insulin." (PMID 21226935, 2011). "Forty patients with type 2 diabetes already being treated with two oral anti-diabetic drugs or insulin treatment and who showed deterioration of their glucose metabolism (i.e. HbA1c >7.5), were treated." (PMID 22196251, 2011). "This observational study evaluated abundant socio-demographic and clinical data from patients with non-insulin-treated Type 2 diabetes in outpatient practices in Spain." (PMID 21294772, 2011). "We found that a number of KEGG terms were common between the two tissue types, including MAPK signaling pathway, Insulin signaling pathway, Type II diabetes mellitus and Adipocytokine signalling pathway." (PMID 22102887, 2011). "The expression and secretion of ApoC III is increased in insulin resistant states and plasma circulating levels are higher in metabolic syndrome and type II diabetes." (PMID 22073239, 2011). "Insulin lispro and insulin glulisine have been shown to be equivalent on all glucose infusion measures in patients with type 2 diabetes, with the exception of a 0.5 mmol/l lower glucose excursion with insulin glulisine in type 2 patients with obesity." (PMID 21410860, 2011). "Our present results suggest that haploinsufficiency of IGF-1R increases the probability for developing type 2 diabetes by diminishing peripheral insulin action and by preventing glucose stimulated compensatory increase in insulin secretion." (PMID 22132081, 2011). "One particularly relevant example is type 2 diabetes, characterized by a reduction in insulin-sensitivity." (PMID 22102829, 2011). "While BAD protein was expressed in both groups, p-BAD protein was virtually absent in β-cells in the diabetic group suggesting enhanced apoptosis in the pancreases from the type 2 diabetes cases who also exhibited blunted insulin signaling." (PMID 22140505, 2011). "This agrees with studies conducted on HIV-negative people with type 1 and type 2 diabetes who have reduced myocardial glucose utilization rates and myocardial glucose utilization per unit insulin." (PMID 22151886, 2011). "In a previous paper we argued that the present insulin resistant pig model resembled type 2 diabetes." (PMID 21756316, 2011). "Among participants with Type 2 diabetes, the similar results about the association of fetuin-A with HOMA-IR and fasting serum insulin concentrations were found." (PMID 21556362, 2011). "Owing to biological variation in fasting insulin levels, values for fasting sample-derived indices are more reliable in subjects with normal glucose tolerance than in individuals with type 2 diabetes." (PMID 22112229, 2011). "First isolated in 1921 and used as a treatment of type 1 diabetes in 1922, insulin has advanced from early animal to biosynthetic human and analogue preparations and is increasingly used to treat type 2 diabetes at various stages of disease progression." (PMID 21410860, 2011).
type 2 diabetes (continued). "Reduced heart and skeletal muscle glucose or FDG metabolism under insulin clamping conditions in patients with type 2 diabetes and coronary artery disease (CAD) has been reported." (PMID 21841971, 2011). "A number of these medications used for treating Type 2 diabetes, including insulin, themselves can result in weight gain." (PMID 21480973, 2011). "It has been recognized for several decades that overt type 2 diabetes is delayed for a considerable period by the ability of pancreatic islets to compensate for the ambient insulin resistance, glucose toxicity and amyloid deposition." (PMID 22140505, 2011). "The majority of the participants (82%) were diagnosed with type 2 diabetes more than five years previously and 44% received a combination of oral medication and insulin for their condition." (PMID 21958233, 2011). "Accumulated evidence suggests that HDL enhancement play a beneficial role in maintaining glucose homeostasis via insulin-dependent and -independent pathways in type 2 diabetes mellitus." (PMID 21886796, 2011). "Thirty East young Asian American adult volunteers (27.6±5.5 years) with type 1, type 2 diabetes or controls underwent hyperinsulinemic euglycemic clamp to assess insulin resistance and DEXA to assess adiposity." (PMID 22164267, 2011). "It is well established that plasma insulin level is decreased due to improved insulin sensitivity in tissues (the liver and muscle, two major targets of insulin action) in obesity and Type 2 diabetes." (PMID 21999347, 2011). "Type 2 diabetes arises when the endocrine pancreas fail to secrete sufficient insulin to cope with metabolic demands, due to acquired β-cell secretory dysfunction and insulin synthesis suppression." (PMID 21533167, 2011). "Case 3 is a 54-year-old Japanese man who had been diagnosed with type 2 diabetes 22 years earlier and had been using different types and doses of insulin since that diagnosis." (PMID 21443773, 2011). "On the other hand, the insulin signal transduction signal was impaired in the controls, as also described in other insulin resistant states (diabetes type 2)." (PMID 22249794, 2011). "In type 2 diabetes, hepatic glucose production becomes insensitive to insulin while TG production remains responsive resulting in selective hepatic insulin resistance." (PMID 21479224, 2011). "Thiazolidinediones (TZD), agonists of the peroxisome proliferator-activated receptor (PPAR)γ, enhance insulin sensitivity and improve metabolic control in patients with type-2 diabetes." (PMID 19233878, 2011). "Type 2 diabetes is characterized by progressive insulin resistance and pancreatic beta-cell dysfunction resulting in key defects in insulin secretion and function." (PMID 21529363, 2011). "This randomized controlled study investigated the effect of postmeal insulin glulisine administration on weight gain and glycaemic control in patients with type 2 diabetes." (PMID 21812890, 2011). "This animal model of type 2 diabetes is characterized by not only major impairment in beta cell function, but also insulin resistance in muscle and liver." (PMID 23675229, 2011). "Patients with type 2 diabetes and obese, insulin resistant individuals generally have 30% less mitochondria in their muscles than normal age-matched individuals." (PMID 21589859, 2011). "These problems include injection site bleeding and bruising which can occur during the treatment of Type II diabetes in addition to problems with the pharmaceutical quality control of insulin." (PMID 22272138, 2011). "Controlling post-meal hyperglycaemia with prandial + basal insulin in patients with Type 2 diabetes attenuates meal-induced increases in high-sensitivity C-reactive protein, interleukin-6 and tumour necrosis factor α compared with basal insulin." (PMID 21517955, 2011). "MicroRNA-133a is abundantly expressed in muscle tissue, and insulin-mediated down-regulation of miR-133a levels in human skeletal muscle is attenuated in Type 2 diabetes." (PMID 20520763, 2010).
type 2 diabetes (continued). "Subjects with type 2 diabetes showed significantly decreased insulin sensitivity and significantly increased soluble serum HER-2 concentration." (PMID 20184722, 2010). "Although the earliest secretory defect in the development of type 2 diabetes is a drop in the first-phase insulin release, a decreased capacity for maximal insulin release is seen prior to a reduction of basal insulin." (PMID 21162746, 2010). "Type II diabetes is a heterogeneous disorder that involves resistance of glucose and lipid metabolism in peripheral tissues to the biological activity of insulin and inadequate insulin secretion by pancreatic β cells." (PMID 20370896, 2010). "Consistently, melatonin, a major regulator of circadian rhythms, has been shown to influence both insulin secretion and glucose homeostasis, and both melatonin secretion and circadian rhythm are impaired in type 2 diabetes patients." (PMID 20398260, 2010). "For example, the chemokine CXCL10 is highly expressed in islets isolated from individuals with type 2 diabetes and has been shown to impair insulin secretion and promote β-cell apoptosis via TLR4." (PMID 20814545, 2010). "This study shows that vascular insulin sensitivity was preserved during treatment with carvedilol while blunted during treatment with metoprolol in patients with type 2 diabetes." (PMID 20500877, 2010). "Activation of PPAR induced insulin sensitivity in type 2 diabetes and promoted tissue uptake of homocysteine; these resulted in lowering of plasma homocysteine levels." (PMID 20613990, 2010). "We carried out a study to confirm if the high CD26/DPPIV gene expression among the HIV-R were concordant with high blood protein levels and its correlation with clinical type 2 diabetes and other perturbations in the insulin signaling pathway." (PMID 21108831, 2010). "ADMA and NO have been found to be significant determinants of insulin insensitivity, a common feature of type 2 diabetes." (PMID 21532773, 2010). "A similar randomized open label, cross over study has been performed in 16 patients with type 2 diabetes, using 150 and 300 U oral insulin (Capsulin) and 12 IU regular insulin." (PMID 21059246, 2010). "Most of the type 2 diabetes mellitus (T2DM)-associated genes are mainly involved both in β-cell function and peripheral insulin sensitivity." (PMID 22399922, 2010). "A major and progressive defect in type 2 diabetes is the relative reduction in the ability of glucose to trigger insulin secretion from beta cells." (PMID 22615610, 2010). "It is claimed that adolescence is a risky period for the development of type 2 diabetes, because the transient physiological status in insulin resistance induces an extra stress on the beta cells in the pancreas." (PMID 21274322, 2010). "A recent randomised, placebo-controlled trial evaluated the effects of metformin on clinical outcomes in 390 insulin-treated type 2 diabetes patients followed for 4.3 years." (PMID 20089006, 2010). "It is well recognized that PPARγagonists have therapeutic applications as insulin sensitizers in type 2 diabetes or as anti-inflammatories." (PMID 19746174, 2010). "Increasing β-cell stress with subsequent failure to release sufficient amounts of biologically active insulin is thought to precede the deterioration of blood glucose control in individuals with type 2 diabetes treated with oral agents." (PMID 20415692, 2010). "Another head-to-head study was a double-blind, randomised, crossover study in subjects with type 2 diabetes that included continuous glucose monitoring after careful insulin titration over several days." (PMID 20618882, 2010). "In our recent study we decipher a new function for these factors in the control of insulin secretion and open up new avenues for the treatment of metabolic diseases, in particular type 2 diabetes." (PMID 20181095, 2010).
type 2 diabetes (continued). "A prerequisite for the development of impaired glucose tolerance (IGT) and type 2 diabetes is a decline in the capacity of the islet cells to secrete insulin." (PMID 21162746, 2010). "The co-localization of OX1R and INS is further confirmed by the fact that a similar pattern was seen in the islet of GK rats, an animal model of type 2 diabetes, where hyperglycaemia is much milder." (PMID 20062799, 2010). "The proportion of type 2 diabetes patients with fear of hypoglycaemia was 50% among those on insulin and 26% among the others." (PMID 20132542, 2010). "Four head-to-head clinical trials comparing insulin glargine and insulin detemir have been published, including one study in type 1 diabetes and three in type 2 diabetes." (PMID 20618882, 2010). "Therefore, our findings of a marked overall decrease in fasting and postprandial IP levels after the initiation of basal insulin treatment might have important implications not only for metabolic control, but also for cardiovascular risk reduction in individuals with type 2 diabetes." (PMID 20415692, 2010). "A second 52-week study compared insulin detemir with insulin glargine administered as add-on therapy to OADs in 582 insulin-naïve subjects with type 2 diabetes." (PMID 20618882, 2010). "An animal study showed that insulin sensitizing treatment is sufficient to abrogate type 2 diabetes-mediated mammary tumor progression." (PMID 24281091, 2010). "This particular cell type controls insulin secretion through a fine-tuned process, which dregulation have important pathological consequences, such as observed during type 2 diabetes." (PMID 20181095, 2010). "This non-interventional study assessed clinical outcomes in people with type 2 diabetes starting insulin therapy using each of the four usual insulin preparations." (PMID 20946269, 2010). "In doing so we inevitably also excluded type 2 diabetes patients treated with an intensive insulin scheme, accounting for about a quarter of the type 2 patients treated with insulin in 2003 (personal communication ND, IPH)." (PMID 20630062, 2010). "Because of its involvement in insulin signaling and immune responses which are the key modulating pathways in type 2 diabetes and obesity, DOK5 seems to be a convincing positional and functional candidate for type 2 diabetes and obesity." (PMID 20187968, 2010). "In the present study, a 60 mg/kg dose of STZ was found to induce type 2 diabetes since the levels of immunoreactive insulin were still measurable at 24 hr after STZ." (PMID 20804590, 2010). "Type 2 diabetes is characterized by a decrease in β-cell mass and function either alone or in combination with insulin resistance, which results in an insufficient insulin production and subsequent hyperglycemia." (PMID 20520763, 2010). "Exercise training positively affects body composition, energy expenditure, glucose homeostasis and insulin requirements and thus, remains a cornerstone in the prevention and treatment of type 2 diabetes mellitus (T2DM)." (PMID 20593012, 2010). "In summary, this study provides evidence that the IITQ is a reliable instrument for assessing a broad range of patient reported outcomes in individuals with type 1 or type 2 diabetes, especially those taking inhaled insulin." (PMID 20334647, 2010). "We assumed that one of the major differences between normal-weight and overweight patients with type 2 diabetes was the ability of insulin secretion." (PMID 20181219, 2010). "Further, we investigated association of DOK5 SNPs with quantitative traits related to type 2 diabetes including fasting glucose, HbA1c, insulin, C-peptide, hsCRP, total cholesterol, HDL, LDL, triglyceride, creatinine, urea and uric acid." (PMID 20187968, 2010). "In type 2 diabetes, basal proinsulin immunoreactivity contributes approximately 2-3 times more to insulin immunoreactivity than in healthy subjects." (PMID 21122092, 2010).
type 2 diabetes (continued). "Baboons and humans also appear to develop similar metabolic disorders; earlier studies have documented spontaneous obesity, insulin resistance, and a form of adult-onset diabetes in captive baboons." (PMID 21034486, 2010). "I am confident in my ability to appropriately adjust the insulin dose among patients with type 2 diabetes whom I have started on insulin." (PMID 20097652, 2010). "Insulin induced a significant decrease in HbA1C, that approached the recommended level in type 2 diabetes (7.5± 0.9%)." (PMID 20721344, 2010). "Type 2 diabetes is a multifactorial disease characterized by decreased insulin secretion and decreased insulin action at target tissues." (PMID 21151568, 2010). "It is presently being studied in a phase 3 trial in type 2 diabetes, as well as a phase 1 trial in type 1 diabetes, and is perhaps in the most advanced development stage of all oral insulin." (PMID 21059246, 2010). "Increased fasting plasma glucose levels in patients with type 2 diabetes are largely attributable to reduced hepatic sensitivity to insulin leading to overproduction of glucose by the liver during the overnight fast." (PMID 20860758, 2010). "GLP-1 is secreted in response to nutrients and its levels are decreased in type 2 diabetes; it acts stimulating glucose-dependent insulin release from the pancreatic islets and this is the major advantage over sulfonylureas, as it prevents hypoglycaemia." (PMID 27713388, 2010). "It is well recognised that patients with type 2 diabetes tend to gain weight when using insulin, with 16-week average gains of 0.5–6 kg for injectable and 2.7 kg for inhaled insulin." (PMID 20370840, 2010). "It is well known that insulin resistance and increased insulin secretion for long periods are characteristics of type 2 diabetes both before and after disease onset." (PMID 20184722, 2010). "The sulfonylureas and related drugs used in type 2 diabetes stimulate insulin by closing K+ ATP channels in pancreatic β cells." (PMID 21264118, 2010). "Subjects comprised type 2 diabetic patients aged 20-79 years, treated with twice daily premixed insulin or insulin analogue formulations." (PMID 20438630, 2010). "Administration of GLP-1 to individuals with type 2 diabetes increases insulin secretion and produces a sustained dose dependent reduction in plasma glucose levels in concert with a reduction in body weight." (PMID 22615610, 2010). "The 3-year results of the Treating to Target in Type 2 Diabetes (4-T) study suggest that most patients are likely to need a second type of insulin." (PMID 20880343, 2010). "Changes in gene expression in pancreatic beta-cells from type 2 diabetes (T2D) should provide insights into their abnormal insulin secretion and turnover." (PMID 20644627, 2010). "Under diabetic conditions, chronic hyperglycemia and subsequent augmentation of reactive oxygen species (ROS) deteriorate β-cell function and increase insulin resistance which leads to the aggravation of type 2 diabetes." (PMID 20182627, 2010). "The aim of this study was to examine the effect of metoprolol versus carvedilol on endothelial function and insulin-stimulated endothelial function in patients with type 2 diabetes." (PMID 20500877, 2010). "Adults of South Asian origin living in the United Kingdom have high risks of type 2 diabetes and central obesity; raised circulating insulin, triglyceride, and C-reactive protein concentrations; and low HDL-cholesterol when compared with white Europeans." (PMID 20421924, 2010). "The progressive impairment of β cell function and increased insulin demand as tissue becomes insulin resistance are core pathophysiologic defects in the development of hyperglycemia in type 2 diabetes." (PMID 20470376, 2010). "A number of comparative studies have evaluated the various insulin preparations used to begin insulin therapy in people with type 2 diabetes." (PMID 20946269, 2010).